NKAPP1 (NFKB activating protein pseudogene 1)
Synonyms: FLJ36576; formerly CXorf42
Gene: Transcribed processed pseudogene on chromosome X (120,238,193 to 120,245,099, reverse strand). Ensembl gene ENSG00000233382.
Diseases named in the same sentence as NKAPP1 in open-access papers:
NKAPP1 is named in the same sentence as 1 disease in open-access papers, as found by Europe PMC text mining. Sharing a sentence is not in itself a finding about the gene and the disease. The quoted sentences say what the papers report.
cervical squamous cancer (1 paper, 2022). "From survival curves, it can be seen that the low expression of ASPH and high expression of NKAPP1 may lead to increased sensitivity to radiotherapy, thus improving cervical squamous cancer patients’ efficacy." (PMID 35965520, 2022). "We identified two genes, ASPH and NKAPP1, as both genes affecting radiotherapy sensitivity and survival by analyzing the included GEO database on radiotherapy sensitivity in intermediate and advanced squamous cervical cancer, using bioinformatics methods with relevant databases." (PMID 35965520, 2022).